CD34 (CD34 molecule)
Diseases named in the same sentence as CD34 in open-access papers (continued):
Sharing a sentence is not in itself a finding about the gene and the disease.
diabetes (88 papers, 2009 to 2026). "Diabetes was also shown to be significantly associated with a reduction in the number of CD34 + KDR + and KDR + EPC subtypes." (PMID 39186241, 2024). "In patients with diabetes, the association was the opposite, with a 55% reduction in the proportion of migrated CD34+/CXCR4+ cells." (PMID 36465463, 2022). "Linagliptin specifically has been shown to be protective for both macrovascular and microvascular complications of diabetes via improvement in tissue remodeling associated with accumulation of CD34+ cells." (PMID 32493344, 2020). "We found that subjects with lower levels of CD34+/AC133+/CD31+/CD45dim cells tended to have a higher prevalence of diabetes, higher HbA1c levels and higher CVD risk scores." (PMID 30321232, 2018). "The major findings in this study were that preconception diabetes is associated with failure to respond to pregnancy-driven elevations in CPCs (CD34+CD45dimSSlow cells) and CACs (CD133+KDR+ and CD133+KDR- cells)." (PMID 28278173, 2017). "In individuals with diabetes, circulating CD34+ cell numbers predict cardiovascular dysfunction and risk better than CD34+VEGFR2+- and CD133+-based populations." (PMID 24713821, 2014). "In addition, higher DCSI scores were associated with increased CD34+ cell percentage, suggesting a link between diabetes severity and BM cellular composition." (PMID 42290843, 2026). "So, diabetes-induced loss of CAC or CD34+ (vascular reparative cell) may have a role in the creation of vascular dysfunction in COVID patients and as such viral myocarditis, heart failure and cardiac arrest have been found in the patients." (PMID 33442728, 2021). "Similarly, acid sphingomyelinase (ASM) activation in CD34+ reparative cells of diabetics is associated with their impaired functionality and measurements of ASM activity can likewise be used to predict vascular repair capacity and vascular health in diabetics." (PMID 30321232, 2018). "However, only low levels of the CAC-3 subtype (CD34+/AC133+/CD31+/CD45dim) were associated with a higher incidence of diabetes, higher HbA1c levels, higher CVD risk scores and measured impairments in vascular function." (PMID 30321232, 2018). "Furthermore, there is evidence that the release of these cells is regulated in a circadian manner and it has been recently reported that the diurnal release of CD34+ cells with high levels of ASM is disrupted with rhythmicity loss in diabetics." (PMID 30321232, 2018). "The administration of Curcumin (Cu) and Rutin (R), whether individually or in combination, resulted in a reduction of the immunohistochemical markers CD3, CD20, and CD34 within the gingival tissues of Wistar rats afflicted with diabetes-associated periodontal disease." (PMID 38793109, 2024). "Another study used saRNAs to differentiate adult human CD34+ cells into insulin-secreting cells to treat diabetes." (PMID 40985895, 2025). "Participants with diabetes had significantly supressed EPC numbers (CD45-CD34 + CD133 + KDR+) and CD34 + KDR + and KDR + EPC subtypes." (PMID 39186241, 2024). "As miR-106b-3p was shown to be significantly upregulated in T1DM, this is congruent with studies showing that diabetes is related to reduced levels and performance of CD34+ cells." (PMID 38255276, 2024). "Another study that evaluated use of a biodegradable polymer DES with anti-CD34+ antibody coating in Asian and European patients found a higher incidence of diabetes in Asian patients, similar to our ethnic minority population." (PMID 38776038, 2024). "A linear correlation between the decrease in the number and functionality of circulating progenitor cells (including CD34+ cells) and the severity of diabetes and its vascular complications has been demonstrated." (PMID 37895025, 2023). "In this study, the biomarker function of CD34, which has been widely used for other cells, was evaluated for islet β-cells during diabetes." (PMID 36467676, 2022).
diabetes (continued). "In the present study, the potential of CD34 as an islet β-cell biomarker and as a β-cell transdifferentiation biomarker in diabetes was explored." (PMID 36467676, 2022). "Determine if myocardial infarct severity and diabetes interactively influence the migratory activity of CD34+/CXCR4+ progenitor cells and if the migratory test predicts cardiac outcomes." (PMID 36465463, 2022). "- Engrafted with HLA-DQ8 human fetal thymus and CD34+ fetal liver cells into HLA-DQ8 transgenic mice.- Develop diabetes after low dose STZ injections and autologous HLA-DQ8 insB9-23 TCR transfer or insB9-23 immunization.- Insulitis." (PMID 35498419, 2022). "The progression of diabetes can be predicted by monitoring the expression of CD34 in the islet structure of patients with diabetes." (PMID 36467676, 2022). "We document the interaction between infarct and diabetes on the migratory activity of CD34+/CXCR4+ cells." (PMID 36465463, 2022). "The study determined that different doses of diclofenac sodium have different effects on different groups of diabetes mellitus cells CD34-megakaryocytes." (PMID 35186138, 2022). "The proportion of number and area of CD34-positive labeled cells are gradually increasing as the degree of diabetes progresses." (PMID 36467676, 2022). "Statistical analysis revealed that the expression of CD34 was negatively correlated with the number of insulin-labeled islet β-cells during diabetes progression in dose-dependent fashion in alloxan-induced diabetes models." (PMID 36467676, 2022). "The flow cytometry assay shows that the number of circulating EPCs (CD34+/VEGFR2+) significantly decreases in the diabetes group, while PCB2 treatment significantly preserves the circulating EPC number compared to diabetic mice." (PMID 33215883, 2021). "To determine how diabetes alters the composition of wound bed myofibroblasts, we examined the relative abundance of CD34+; SCA1+, and CD29High myofibroblast subsets in wound beds five days post-wounding (PW) in db/+ and db/db mice." (PMID 34944568, 2021). "The mobilization of CD34+ stem cells is impaired in patients with diabetes mellitus, while patients who previously received G-CSF have a decreased probability of achieving a CD34+ stem cell count of >50/μL." (PMID 34943774, 2021). "We believe CD34+ cells can act as a valuable biomarker for assessment of endothelial function, in a setting of diabetes and can help provide valuable clinical information leading to appropriate therapeutic intervention choices." (PMID 33581737, 2021). "Though the molecular mechanisms mediating numerical and functional alteration of CD34+/CD133+ HSPCs in diabetes are still largely obscure, BM is emerging as the original core of HSPC dysfunction." (PMID 32485847, 2020). "Overall, we believe that cellular parameter such CD34+ progenitor cell study along with clinically relevant parameters such as arterial stiffness helps to evaluate a diabetes medication quite thoroughly." (PMID 32493344, 2020). "We believe CD34+ cells can act as a valuable biomarker for assessment of endothelial function, in a setting of diabetes and similarly urine exosome analysis can help elucidate and predict renal function improvement." (PMID 32493344, 2020). "In summary, we have found that low levels of several CAC subtypes were predictive of diabetes and that one in particular, characterized as CD34+/AC133+/CD31+/CD45dim, was indicative of both diabetes and endothelial dysfunction." (PMID 30321232, 2018). "Recently, our group found that the number of circulating mesenchymal-like cells (CD34−/CD105+) is significantly decreased in type 2 diabetes mellitus (T2DM) patients and is negatively correlated with the progression of chronic diabetic complications." (PMID 30409193, 2018). "Consistent with previous reports, we observed a significant decrease in CACs (Flk-1+/Sca-1+/CD34+ cells) in mice after 3 months and 6 months of diabetes." (PMID 29700294, 2018).
diabetes (continued). "We found that subjects with low levels of CD34+/AC133+/CD31+/CD45dim cells (CAC-3) had a significantly higher incidence of diabetes (p = 0.004), higher HbA1c levels (p = 0.049) and higher CVD risk scores." (PMID 30321232, 2018). "BM-CACs (Flk-1+/Sca-1+/CD34+ cells) demonstrate a 1.5-fold increase after 3 months of diabetes followed by a twofold decrease after 6 months of diabetes." (PMID 29700294, 2018). "Here we addressed the dual impacts of diabetes and pregnancy on CPCs (CD34+CD45dimSSlow), CACs (CD34+CD45dimSSlow expressing CD133 and/or KDR) and on early outgrowth colonies." (PMID 28278173, 2017). "The aim of this study was to investigate the effect of metformin on the angiogenic properties of CD34+ cells under conditions mimicking acute myocardial infarction in diabetes." (PMID 26861446, 2016). "Individuals with diabetes and vascular complications have reduced numbers of both CD34+ cells and ECFCs." (PMID 27936469, 2016). "In the recent past we have investigated the effect of exercise on diabetes and prediabetes patients using CD34+ progenitor cells." (PMID 26652025, 2015). "We demonstrated that B2 receptor (B2R) expression on circulating CD34+ cells was significantly reduced in patients with diabetes mellitus (DM) as compared to healthy controls." (PMID 26360782, 2015). "For example, circulating CD34(+) and CD14(+) PBMCs express and secret the antiomiR-126, and an alteration of angiomiR-126 expression in CD34(+) PBMCs in diabetes provides a novel pathway causing impaired proangiogenic effects." (PMID 24865854, 2014). "Recently, we have shown that TGFβ1 mediates vasoreparative dysfunction in CD34+cells from diabetics and that the transient blockade of the expression of TGFβ1 or PAI-1, the main gene target of TGFβ, restores vasoreparative function." (PMID 24713821, 2014). "Previously, we showed that transient inhibition of TGF- β1 resulted in correction of key aspects of diabetes-induced CD34+ cell dysfunction." (PMID 24223881, 2013). "Since levels of PAI-1 increase in endothelial cells as a result of exposure to high glucose, high insulin, oxidative stress, or TGF-β1, we measured endogenous secretion of PAI-1 in CD34+ cells from individuals with diabetes." (PMID 24223881, 2013). "In diabetics, circulating levels of CD34+ cells are negatively correlated with the percentage of apoptotic CD34+ cells, and thus EPC levels are decreased in the peripheral blood due to EPC apoptosis and/or bone marrow retention." (PMID 22418586, 2012). "We however observed an attenuated response at 2 hours post glucose challenge for CD34+ and CD133+CD34+ cells in the pre-diabetes group compared to the NGT group." (PMID 21219665, 2011). "In addition, both the number and proliferative potential of CD34+ EPCs are known to be attenuated in patients with diabetes." (PMID 41294818, 2025). "In a study involving mice with diabetes, human endothelial progenitor cells (CD34+ cells) were injected locally into the wound bed, which led to neovascularization in conjunction with recipient endothelial cells, increased wound vascular density, and a high rate of wound closure." (PMID 38377120, 2024). "We found that HTN and BMI were positively associated with CD34+CD133+ EPCs in FHS, but other studies show that aging diseases like cardiovascular diseases and diabetes and the absence of healthy aging are associated with decreased CD34+CD133+ EPCs." (PMID 38854406, 2024). "Interestingly, although the level of chemokine SDF-1 was shown to be almost ~ 3-fold higher in participants with diabetes, as reported in the literature, the number of CD34 + CD133 + KDR + and KDR + cells were substantially suppressed." (PMID 39186241, 2024). "However, with the improvement in cardiovascular health and increased physical activity in patients with diabetes, their number of CD34+ cells increased." (PMID 37895025, 2023).
diabetes (continued). "A similar pathophysiological mechanism—oxidative stress and reduced bioavailability of nitric oxide in a hyperglycaemic state—could also be attributed to the depletion of the number and function of CD34+ cells in patients with diabetes mellitus." (PMID 37895025, 2023). "Thus, painful MVD with respect to painless DDPN patients showed an increase in CD31- and CD34-positive BVs, mainly in the reticular dermis in long-term and short-term diabetes, respectively." (PMID 38054043, 2023). "Compared with the control group, the proportion of INS-positive area in the diabetes model group decreased significantly (from 0.7243 ± 0.0131 to 0.1258 ± 0.0102), whereas the proportion of CD34-positive area increased significantly (from 0.1375 ± 0.00923 to 0.5364 ± 0.0266)." (PMID 36467676, 2022). "Furthermore, the proportion of CD34-positive cells, which were also positive for glucagon, was significantly increased in alloxan-induced diabetes models." (PMID 36467676, 2022). "For further verifying the relationship between CD34 and islet β-cell failure in the progression of diabetes, IF staining and statistical data visualization were performed in the pancreas sections of five rats that were dosed with the different concentrations of alloxan." (PMID 36467676, 2022). "Moreover, with the progression of diabetes, the expression of CD34 in islets increased and the proportion of expression in the original β-cells increased." (PMID 36467676, 2022). "Using flow cytometry, we investigated if diabetes alters the relative abundance of CD34+; SCA1+, and CD29High mesenchymal cells in the skin and determined if colocalization with profibrotic markers CD9 and CD26 was different in db/db skin compared to db/+ control skin." (PMID 34944568, 2021). "We identified a serum‐free Quantity and Control culture method (QQc) that could restore the functionality of BM‐derived murine diabetic c‐kit+Sca‐1+lin− (KSL) cells and peripheral blood CD34+ cells of patients with diabetes." (PMID 33599112, 2021). "Increased glomerular CD34 expression is related to age and diabetes." (PMID 33714204, 2021). "Saxagliptin, in combination with metformin, can help improve endothelial dysfunction in early diabetes before macrovascular complications appear, and this effect was potentially related to upregulation in CD34+ endothelial progenitor cells for antioxidant SOD1." (PMID 34531738, 2021). "In conclusion, we have demonstrated the efficacy of CD34+ cell therapy for healing of cutaneous wounds in mice with diabetes, which occurred by resolving inflammation, increasing, angiogenesis, enhancing epithelialization and improving granulation tissue formation." (PMID 31182750, 2019). "However only one cell type predictive of diabetes, CAC-3 (CD34+/AC133+/CD31+/CD45dim), was also positively associated with RHI score; thus high levels of cells were associated with a high RHI score and a healthy endothelium." (PMID 30321232, 2018). "The number of CD34+ cells present in the MNCs pool is relatively low in patients with diabetes." (PMID 29724198, 2018). "Therefore, endothelial progenitor cells (EPCs, defined here as CD34+ cells), which are specialized cells responsible for endothelial repair and neo-angiogenesis, play an important role in diabetes." (PMID 29724198, 2018). "It is interesting that an analogous cell type only lacking AC133 expression (CAC7: CD34+/AC133-/CD31+/CD45dim) displayed associations with neither diabetes outcomes or endothelial function." (PMID 30321232, 2018). "We believe CD34+ cells can act as a valuable biomarker for assessment of endothelial function, in a setting of diabetes and can help provide valuable information using cellular data, to support or refute findings from other cardiovascular outcome trials in diabetes." (PMID 29724198, 2018). "Patients with complicated diabetes showed a depletion of CD34+NK1R+ HSPCs in their BM and PB." (PMID 26358583, 2015).
diabetes (continued). "Our focus on PAI-1 arose from the observation that diabetic individuals protected from vascular complications despite less than optimal diabetes control showed lower PAI-1 transcript levels in their CD34+ cells, and these same individuals expressed higher levels of uPA." (PMID 24223881, 2013). "Moreover, the frequency of CD34/45+ BM-CPCs in ischemic tissue is further impaired by diabetes in patients with IHD." (PMID 22118372, 2011). "Therefore, the rs2396295 and rs892204 SNPs located in the CD34 gene may affect endothelial progenitor cell function and vascular repair, particularly in diabetes." (PMID 40650017, 2025). "These include, for instance, age and gender, diabetes, family history, hypertension and hypercholesterolemia, all of which are associated with a quantitative reduction and functional inhibition of PCs (both mature, i.e., CD34+/CD133+/KDR+, and less mature, i.e., CD34+)." (PMID 35805178, 2022). "Furthermore, increased CD34-positive α-cells in the pancreatic islets of diabetes models indicated that some β-cell may undergo transdifferentiation rather than apoptosis in the progression of diabetes and also lose the function of INS secretion." (PMID 36467676, 2022). "In the Framingham Heart study, which included 10% of individuals with diabetes, higher SDF-1α values were directly and independently associated with the risk of heart failure and 10-year all-cause mortality and inversely with CD34+ (bone marrow-derived) circulating cell phenotypes." (PMID 28231835, 2017). "We reasoned that the PAI-1 system could provide valuable insights into the function of CD34+ cells and, therefore, effective regulation of this system in diabetes might confer an enhanced reparative function of these cells and protection from the development of vascular complications." (PMID 24223881, 2013). "The purpose of this study in asymptomatic Old Order Amish men (n = 90) without hypertension or diabetes was to determine if PC count, as determined by CD34+ cell count in peripheral blood, was associated with 10-year risk of cardiovascular disease (CVD) and measures of subclinical atherosclerosis." (PMID 20407620, 2009). "CD34 and GLU were highly colocalized in the diabetes model, and their expression in the diabetes model was significantly higher than that in the control group." (PMID 36467676, 2022). "Thus, the present study demonstrated that CD34 is expressed on islet α-cells, and its number is linearly and negatively correlated with the number of islet β-cells, suggesting that CD34 can be used as a prospective biomarker for islet β-cells in the early diagnosis of diabetes." (PMID 36467676, 2022). "Post-challenge glucose was found tobe an independent determinant of the levels of both CD34+ and CD34+/KDR+in individuals with T2D and pre-diabetes." (PMID 37680455, 2022). "Despite this, we showed that the increased circulating HPCs and EPCs from pre- to post-exercise in the type 1 diabetes group, CD34+ HPCs, CD34+VEGFR2+, CD34+VEGFR2+CXCR4+ EPC counts were significantly attenuated compared to the non-diabetes controls." (PMID 34267242, 2021). "To interrogate how diabetes impacts the function of specific myofibroblast subsets, we FACS-isolated CD34+; SCA1+ and CD29High myofibroblasts from wound beds five days PW and examined the expression of genes related to myofibroblast function." (PMID 34944568, 2021). "We attribute the reduction in the population of CD45–CD31+CD34+ EPC and CD45–CD31–Sca1+CD49f+ epithelial precursors in the testes of mice of group 2 to inflammation, obesity, and diabetes." (PMID 33344442, 2020). "Compared with healthy individuals, chronic PD patients with or without diabetes had more CD34 positive blood vessels in gingival tissues." (PMID 37051594, 2023).